CXCL8 (C-X-C motif chemokine ligand 8)
Diseases named in the same sentence as CXCL8 in open-access papers (continued):
Sharing a sentence is not in itself a finding about the gene and the disease.
COVID-19 (continued). "A COVID-19 study revealed the production of proinflammatory cytokines (CXCL-8, IL-6, CCL20, CCL3, CCL4, and IL-12) by dysfunctional mitochondria." (PMID 36092161, 2022). "Remarkably, severe influenza and COVID-19 also converge in elevated levels of chemotactic (CXCL8, CCL2, CCL3, and CXCL10) and activating molecules (G-CSF) acting on monocytes and neutrophils." (PMID 35674675, 2022). "Of more recent relevance, it has been reported that CXCL8 and C5a are present in abundance in hospitalized patients with COVID-19." (PMID 34649250, 2022). "Conversely, solid tumor patients that had elevated levels of inflammatory cytokines IL-6, CXCL8, and lost the coordinate production of anti-virus antibodies developed severe COVID-19 and died." (PMID 36700209, 2022). "Compared to healthy controls, CD16+ monocytes from people with COVID-19 had significantly upregulated expression of genes involved in inflammation including cytokines and chemokines, such as IL-1β, CXCL8, CCL3 (MIP-1α), and CCL4 (MIP-1β)." (PMID 34108966, 2021). "Transcriptional analysis confirms that CXCL8 levels significantly show an upward trend in COVID-19 patients, which triggers the recruitment of neutrophils to aggravate the inflammatory injury." (PMID 35069542, 2021). "Patients with fatal COVID-19 also showed significantly higher plasma levels of the neutrophil recruiting CXCL-8 as well as of the T and NK cell-attracting CXCL-9, as compared to severe and/or mild COVID-19 patients." (PMID 34473805, 2021). "In this study, we focused on TNFα, IL-1β, and IL-6 as known pro-inflammatory markers of acute inflammatory response, along with CXCL8/IL-8 because of its potent role in the recruitment and activation of neutrophils, commonly elevated in patients with COVID-19." (PMID 34360706, 2021). "Although the profile of inflammatory markers is highly variable between patients, a general phenotype of severe COVID-19 is characterized by elevated IL-6, IL-8, IL-10, TNF-alpha, CCL2, CCL3, and CXCL8." (PMID 34830356, 2021). "Many studies have reported an increase in IL-6, IL-1β, and CXCL-8 in severe patients with COVID-19, which are also important factors that induce granulocyte activation and NET release." (PMID 33557911, 2021). "The expression of CXCL8, which is present in COVID-19 patients, is considered a potential prognostic factor in acute respiratory distress syndrome (ARDS) and lung injury." (PMID 33345622, 2021). "Transcriptional analysis of BAL fluid and peripheral blood mononuclear cells showed that elevated CXCL2 and CXCL8 chemokines contribute to neutrophils recruitment and aggravate the inflammatory response in COVID-19 patients." (PMID 34912345, 2021). "CXCL8 is produced by several specialized secretory cell types, including those uniquely expanded in COVID-19." (PMID 34352228, 2021). "In our study, increased expressions of CXCL10 and CXCL8 are observed, which also seem to characterize COVID-19." (PMID 33726831, 2021). "Secondly, levels of the main neutrophil chemoattractant CXCL8 were more than 3-fold higher in critical COVID-19 than in MAS, pointing toward a potential neutrophil signature." (PMID 34226537, 2021). "Inflammatory genes such as IL1B, TNF, and CXCL8 were also increased during aging and were further upregulated in COVID-19." (PMID 32780218, 2020). "A leading, indirect pathway is inflammation-driven tumor promotion, particularly through IL-6/JAK–STAT3, IL-1β/NLRP3, TNF-α/NF-κB, and ELR+ CXC chemokines (e.g., IL-8/CXCL8), which are all engaged during COVID-19 and have established roles in lung tumor biology." (PMID 41440526, 2025). "Collectively, these results suggest that suppressing high severity-specific markers (i.e., FOS, CXCL8, and HLA-A) may help prevent COVID-19 progression." (PMID 41155463, 2025).
COVID-19 (continued). "Exposure to CS or nicotine upregulated many genes within AGE-RAGE signalling with high confidence, including CCND1, CXCL8, HRAS, IL6, KRAS and TNF, suggesting that smokers have a hyperactive AGE-RAGE and are therefore more at risk of severe COVID-19." (PMID 38991709, 2024). "Finally, recent attention is paid to the role of CXCL8 and neutrophils in COVID-19 ARDS (vide infra)." (PMID 36725964, 2023). "Comparison of SARS-CoV-2 viral burden in nasal swabs and saliva revealed no sex differences, however males were found to have significantly elevated CXCL8 and IL-18 pro-inflammatory mediators in plasma samples, likely contributing to severe COVID-19 and increased mortality." (PMID 36941580, 2023). "Numerous studies have shown that markers such as IL6 and CXCL8/IL8, as well as certain patterns in multiomics-based studies, might be associated with COVID-19 severity and lethality." (PMID 37310504, 2023). "All of the 6 intersected genes have been reported to associate with COVID-19, including FGFR3, TP63, CXCL2, CCL20, IL1B and CXCL8." (PMID 37497545, 2023). "Moreover, high serum levels of cytokines, such as IL-6, CCL2, CXCL8, CXCL10, IL-2, and IL-10 were associated with COVID-19-related encephalopathy and showed an enhanced systemic inflammatory response." (PMID 36232655, 2022). "Patients with severe COVID-19 typically have increased serum levels of IL-6, IL-8/CXCL8, CXCL9, CXCL10, TNF-α, MCP1/CCL2, RANTES/CCL5, IL-18, and MIP-1α/CCL3, which promote a sustained pro-inflammatory state that may persist for up to 60 days." (PMID 36289507, 2022). "Finally, COVID-19 worsening during hospitalization is also positively correlated with admission plasma levels of IL-8/CXCL8, MCP-1/CCL2, IL-10, and C-reactive protein." (PMID 36035415, 2022). "Moreover, a positive correlation was seen between levels of IL-1β or IL-17A and CXCL8 in the BAL fluid of the patients with COVID-19." (PMID 34793331, 2022). "Additionally, a CXCL-8/IL-8-dysregulated prothrombotic neutrophil phenotype, favoring degranulation and NETosis, was ascribed to thrombotic complications in COVID-19." (PMID 35681519, 2022). "Interestingly, COVID-19 patients had lower levels of most classic inflammatory cytokines, including CXCL8." (PMID 36232655, 2022). "Indeed, elevated levels of IL-8/CXCL8 have also been documented in patients with severe COVID-19, both in plasma and in lung samples." (PMID 36035415, 2022). "In COVID-19, a significant reduction of the inflammatory process related to CCL-2/MCP-1 and CXCL8/IL-8 activity might be associated with the exercise protocol with controlled intensity and duration." (PMID 36685603, 2022). "Significant levels of macrophage chemo-attractants such as CXCL10 and CCL2/MCP-1, as well as neutrophil chemo-attractants like CXCL2 and CXCL8, enhance immune cell migration to the site of infection, which is consistent with mononuclear cell infiltrates in COVID-19 patients’ lung tissues." (PMID 35958594, 2022). "Interestingly, levels of IL-1β and CXCL8 in COVID-19 BAL fluid correlated positively with the elastinolytic and gelatinolytic activities measured." (PMID 34793331, 2022). "Neutrophils from COVID-19 patients demonstrated increased transwell migration towards CXCL-8 compared to AMC (fold change of neutrophils migrated to CXCL-8 vs. vehicle control: 12.15 (51.4) AMC vs. 40.63 (115.2) COVID-19, p = 0.0332) and CAP (9.55 (23.7, p = 0.0332)." (PMID 36139476, 2022). "In this study, Phaseol, Glycyrol and Glyasperin F in licorice may treat COVID-19 to reduce the inflammatory response and promote cell survival by acting on CXCL8, IL2RA, STAT3, and MMP1." (PMID 36120307, 2022). "Although all these preliminary studies were performed with a limited number of patient samples, our findings agree with these reports, demonstrating robust production of the neutrophil-chemoattractant chemokine CXCL8 as a universal COVID-19 mediator in systemic and airway compartments." (PMID 35720401, 2022).
COVID-19 (continued). "The elevation in CXCL8/IL-8 in COVID-19 patients is a common finding supported by multiple studies." (PMID 36012323, 2022). "Network analysis of inflammatory mediators in the nasal mucosa and serum showed an anti-inflammatory response (IL-10 upregulation) and T2 inflammatory (CCL11 and CCL24 upregulation) response with co-existent inflammation (upregulation of IL-6 and CXCL8) in early COVID-19." (PMID 35397798, 2022). "COVID-19 patients who succumb to pneumonia and hypoxia had one hallmark feature of the profound inflammatory state that marked elevation of serum inflammatory cytokines (IL-6, IFN-γ, IL-1β, TNF-α and TGF-β) and chemokines (CCL2, CCL5, CXCL8 and CXCL10)." (PMID 34313585, 2021). "Regarding the downregulated geneset, MHC II molecules, including HLA-DQA1, HLD-DRA, HLA-DRB1, HLA-DMB, HLA-DMA, etc., and cytokine/chemokine genes, including IL1B, TNF, CCL3, CCL4, and CXCL8 were expressed at lower levels in COVID-19 patients, especially those with severe diseases." (PMID 33101705, 2020). "IL-8, or CXCL8, is an important chemokine for the migration of neutrophils to the lungs in acute respiratory distress and the formation of neutrophil extracellular traps in COVID-19." (PMID 33072624, 2020). "In addition, the enrichment of Akkermansia muciniphila populations has been positively associated with levels of pro-inflammatory cytokines such as IL-1β, IL-6, and CXCL8, which could imply potential protective effects during COVID-19." (PMID 40431202, 2025). "Thus, the chemokine antibody signature that distinguished healthy controls from COVID-19 convalescents (autoantibodies to CCL19, CCL22 and CXCL17) was different from the signature associated with COVID-19 severity (autoantibodies to CXCL5, CXCL8 and CCL25)." (PMID 36879067, 2023). "Moreover, a study using bioinformatics analysis and molecular dynamic stimulation has shown that phaseol in licorice may have beneficial effects in reducing the inflammatory response to COVID-19 by inhibiting the activation of CXCL8 and IL2RA." (PMID 36873992, 2023). "Finally, therapies targeting IL-8/CXCL8- or IL-10 activity may offer therapeutic approaches in COVID-19 treatment." (PMID 36035415, 2022). "Interestingly, BAL fluid levels of CXCL8 were specifically shown to be predictive for COVID-19 severity and may also serve as a potential biomarker for predicting COVID-19 progression." (PMID 34793331, 2022). "For instance, while reducing the correlation between DEGs including IL10, CXCL8, NFKB1, ARG1, and SOD2, new strong associations appeared between ELANE, DEFA4, AZU1, CTSG, and LCN2, with an overall tendency to higher relationships amid neutrophil-mediated immunity genes in COVID-19 patients." (PMID 35269470, 2022). "It has been established that pre-treatment with an anti-CXCL8 antibody prevents the development of severe lung injury; thus, targeting this cytokine or its receptor may offer an effective treatment option for COVID-19 patients." (PMID 34276659, 2021). "The highly activated M1 macrophage cluster showed predominant enrichment of pro-inflammatory mediators, including IL1B and CXCL8, which was further supported by our results showing that the highly activated M1 was highly enriched with gene sets from severe COVID-19 patients." (PMID 34315893, 2021). "The COVID-19 high-stage-specific markers (i.e., FOS, CXCL8, HLAA, JAK3, ICAM1, and H2BC4) were overexpressed in higher-stage samples, that is, increased expression levels of the markers were observed in asymptomatic to critical samples." (PMID 41155463, 2025). "In COVID-19, severe outcomes have increased levels of pro-inflammatory and anti-inflammatory cytokines and chemokines, such as IL-6, TNF-α, IL-10, CCL2, CCL3, CXCL8, and CXCL10, among others." (PMID 40881695, 2025).
COVID-19 (continued). "The aim of this work was to evaluate the associations of polymorphisms in the TNF-α, IL-6, IL-8, IL-10, CCL5 and CXCL6 genes with COVID-19 outcomes and with the serum levels of IFN-α, IFN-γ, TNF-α, IL-1Ra, IL-6, IL-7, IL-10, CCL2, CCL3, CXCL8, CXCL10 and GCSF." (PMID 40881695, 2025). "Collectively, we suggest that controlling CXCL8 and S100A9 and the main players HLA class I is crucial to uncover the immune disease-related mechanisms of COVID-19 severity." (PMID 40580453, 2025). "Five chemokines were explored in this study, where 3 of them (MCP-1/CCL2, IL-8/CXCL8, and IP-10/CXCL10) showed a significant increase in COVID-19 patients with further increase in higher severities." (PMID 38855114, 2024). "Transcriptomic studies of COVID-19 patients revealed upregulated cytokine (TNF, CXCL8, IL1B, IL6, IL10, IL12) and chemokine (CCL2, CCL3, CCL4, CCL20, CXCL2, CXCL9, CXCL10) expression in monocytes as one major dysregulation in these patients." (PMID 38391913, 2024). "Although CXCL8 levels were unaltered in both groups, high levels of CCL5 were detected after bLf treatment at 10 mg/mL in the COVID-19 group." (PMID 39483459, 2024). "We note the differential expression of many inflammatory CC chemokines (CCLs) in severe COVID-19, including CCL2, CCL3, CCL8, CCL3L1 and CCL7, and CXC chemokines such as CXCL2 and CXCL8." (PMID 39187683, 2024). "Previously, we showed that the proinflammatory subtype of monocytes (Mon IFI30) accompanies severe Delta COVID-19, and this population yields high expression of IFI30, C15orf48, CXCL8, CSTB, and SPP1 genes." (PMID 39712003, 2024). "Concentrations were significantly higher in the COVID-19+ cohort except for IL-1β, CXCL1, IL-10 and CXCL8." (PMID 38715114, 2024). "Corresponding proteins from many of these DEGs have already been identified as drug targets for the treatment of various diseases such as COVID-19, asthma or rheumatoid arthritis (e.g., CCR2, CCR3, CXCL8, JAK3, HRH, CA4, see clinicaltrials.gov)." (PMID 38242945, 2024). "Several cytokines (GM-CSF and IL-6) and chemokines (MCP-1/CCL2, IL-8/CXCL8, and IP-10/CXCL10) were markedly increased in COVID-19 patients with a significant correlation with disease severity." (PMID 38855114, 2024). "High levels of these molecules, detected after macrophage treatment with VLPs (TNFα, IL-1β, CCL8, CXCL8, CXCL9, CXCL16, CXCL1, and CXCL2), were shown to correlate with severe COVID-19 in other studies." (PMID 38664730, 2024). "The mediators IL-1β, IL-6, IL-10, TNF-α, IL-8/CXCL8, IL-1RA, IL-18/IGIF, and sTNFR1 were all increased in patients with COVID-19 and followed the rate of elevation as clinical worsening progressed." (PMID 36851766, 2023). "Other studies have also indicated severity associated with increased levels of plasma chemokines, such as CCL2, CXCL8, and CXCL10, in severe COVID-19." (PMID 37632046, 2023). "In COVID-19-derived monocytes, TNFα, IL1β, IL6, IL10, CXCL8/IL8, and COX2 were also significantly increased, depending on disease severity." (PMID 37310504, 2023). "The death of some COVID-19 patients is strongly related to cytokine release syndrome (CRS), this is similar to septic patients characterized by excessive IL6, TNFA, IL1B, and CXCL8 levels in their blood." (PMID 36798115, 2023). "Compared with the control group, there was extensive cytokine/chemokine correlations centered on IL-17A, IL-10, IL-6, CCL2, CXCL8, CXCL9 and CXCL10 and fewer correlations with IL-1β in the COVID-19 patients at baseline." (PMID 37662953, 2023). "Transcriptome profiling of in vitro models of the airway epithelium revealed increased expressions of IL-1β, TNF-α, CCL2, CCL20, CCL8, CXCL2, CXCL8, and CXCL16 (all of which are upregulated in severe COVID-19), resulting in lung injury and multiorgan failure." (PMID 37631998, 2023). "The secretion of cytokines and chemokines, including IL6, CXCL8, IL1B, IL10 and CCL2, is significantly increased in COVID-19 AKI." (PMID 37274117, 2023).
COVID-19 (continued). "In the lungs of patients with severe COVID-19, CXCL8 (IL-8) and CXCL1 (GROα) were the predominant CXC chemokines." (PMID 36851549, 2023). "A longitudinal increase in a variety of inflammatory cytokines, including IL6, IL8/CXCL8, and TNFA, in COVID-19 patients has been observed." (PMID 36798115, 2023). "Particularly, many inflammation genes, such as C5AR1, CD55, CSF3R, CXCL8, FPR1, KLF6, and NFKB1A, were significantly upregulated in Neu and Mono cells of the bone marrow of COVID-19 patients." (PMID 37087411, 2023). "In COVID-19, the CXCL8-CXCR1/-2 axis plays an important role through an autocrine forward loop when neutrophils are simultaneously mobilized and activated by CXCL8 and contribute to microvascular thrombosis of the pulmonary vasculature by NETosis." (PMID 37954596, 2023). "Concomitantly, in severe COVID-19, an increase in the initial production of IL6 and IL10 (4/6 days) was seen and maintenance of high levels of CXCL8 at times 4/6 and 15/20 days." (PMID 37515295, 2023). "In post-COVID-19 patients, some plasma cytokines (i.e. TNF-α, IL-18, CXCL8, CXCL10, CCL2, CCL3, and CCL4) remained higher than in HCs, but levels were much lower as compared to hospitalised patients." (PMID 36275702, 2022). "A significant increase in CXCL2, CXCL8, CXCL9, and CXCL16 levels was reported in COVID-19 positive patients with generalized inflammation." (PMID 36016187, 2022). "Compared to NI subjects, COVID-19 patients had significantly elevated levels of IL-6, IL-10, IFN-γ, CCL5, CXCL9, and CXCL10 and decreased levels of CXCL8." (PMID 36287506, 2022). "Within our COVID cohort, nonsurvivors were characterized by higher cytokine levels, especially IL-1RA, IL-6, MCP-1, CXCL8, and CXCL10 than patients who survived COVID-19." (PMID 35359931, 2022). "In fact, of the 13 most abundant mediators in BAL fluid of severe COVID-19 subjects, 11 were chemokines, with CXCL1 and CXCL8 being 200 times more abundant than IL-6 and TNF-α." (PMID 35812400, 2022). "Levels of the inflammasome cytokine IL1B, the neutrophil chemotaxis factor CXCL8, and alarmins S100A8 and S100A9 were comparably elevated in KD and severe COVID-19 compared to FC and HC, respectively." (PMID 36159873, 2022). "Concomitant with enhanced BAL neutrophilia, the major neutrophil chemokine CXCL8 was increased in post-COVID-19 BAL compared with HC BAL, and CXCL8 concentration was significantly correlated with airway neutrophils." (PMID 35151371, 2022). "In agreement with our findings, previous studies evaluating individual serum samples from COVID-19 patients revealed an enhanced and generalized inflammation, featured by a significant increase in circulating IL-6, IL1RA, CXCL8 levels." (PMID 35720401, 2022). "In the blood of patients with moderate and severe coronavirus disease 2019 (COVID-19) there are elevated levels of CXCL1 and CXCL8/IL-8." (PMID 36613652, 2022). "Severe cases of COVID-19 develop cytokine storms characterized by excessive systemic release of multiple cytokines including IP-10 (CXCL10), IL-6, IL-8 (CXCL8), and IL-10." (PMID 35247068, 2022). "Co-targets were 194 genes intersecting with COVID-19, RA-DEGs (GSE55235), and pyroptosis-related genes, including 7 genes: CASP1, CASP8, IL1B, CASP3, JUN, EGFR, CXCL8." (PMID 36532040, 2022). "We observed that CXCL8 (AUC 0.98) and VEGFA (AUC 0.94) were particularly good at predicting COVID-19 outcomes within hematologic cancer patients, while CXCL8 (AUC 0.89) and IL-6 (AUC 0.88) were good predictors for solid tumor patients." (PMID 36700209, 2022). "A higher expression of chemokines (CXCL1, CXCL2, CXCL3, CXCL8 and CXCL16) were also found in the CD4+ TCM and Classical Monocytes in the COVID-19 patients." (PMID 36532041, 2022). "They showed that IL-6, CCL2, CXCL8, CXCL9, and CXCL10/IP10 levels were higher in patients with MIS-C than in those with COVID-19." (PMID 35268506, 2022).